NANOS3 (nanos C2HC-type zinc finger 3)
Description:
Plays a role in the maintenance of the undifferentiated state of germ cells regulating the spermatogonia cell cycle and inducing a prolonged transit in G1 phase. Affects cell proliferation probably by repressing translation of specific mRNAs. Maintains the germ cell lineage by suppressing both Bax-dependent and -independent apoptotic pathways. Essential in the early stage embryo to protect the migrating primordial germ cells (PGCs) from apoptosis.
Synonyms: NOS3; NANOS1L; ZC2HC12C
Tractability: No criterion of Open Targets' tractability assessment is met for any kind of drug.
Gene: Protein-coding gene on chromosome 19 (13,862,063 to 13,880,757, forward strand). Ensembl gene ENSG00000187556.
Subcellular location: Nucleus; Cytoplasm; Cytoplasm, Stress granule; Cytoplasm, P-body
Subcellular location (Human Protein Atlas): Nucleoplasm; Cytosol
Pathways (Reactome):
Reproduction: Specification of primordial germ cells
Gene Ontology:
Molecular function: enzyme activator activity; protein binding; mRNA binding; RNA binding; zinc ion binding
Biological process: germ cell development; mRNA destabilization; negative regulation of translation; oogenesis; regulation of cell cycle; regulation of translation; spermatogenesis
Cellular component: cytoplasm; cytosol; nucleoplasm; nucleus; perinuclear region of cytoplasm; cytoplasmic stress granule; P-body
Genetic constraint (gnomAD): Loss-of-function variants: 13 observed, 14.27 expected, observed/expected ratio (o/e) 0.91, 90% interval 0.59 to 1.45. The upper end of that interval is the gene's LOEUF score, 1.45, which puts it in group 5 of 6, group 1 being the genes least tolerant of losing a copy. Missense variants: 221 observed, 256.36 expected, observed/expected ratio (o/e) 0.86, 90% interval 0.77 to 0.96. Synonymous variants: 119 observed, 114.88 expected, observed/expected ratio (o/e) 1.04, 90% interval 0.89 to 1.21.
Homologues: Orthologues: chimpanzee NANOS3 (99% identical), macaque NANOS3 (95% identical), pig NANOS3 (75% identical), guinea pig NANOS3 (71% identical), dog NANOS3 (68% identical), rabbit NANOS3 (68% identical), mouse Nanos3 (67% identical), rat Nanos3 (65% identical), tropical clawed frog nanos3 (37% identical), zebrafish nanos3 (28% identical), Drosophila melanogaster nanos (23% identical), Caenorhabditis elegans nos-1 (19% identical), and 1 more. Paralogues in human: NANOS2 (31% identical), NANOS1 (24% identical).